MZB1 (marginal zone B and B1 cell specific protein)
Diseases named in the same sentence as MZB1 in open-access papers (continued):
Sharing a sentence is not in itself a finding about the gene and the disease.
pancreatic carcinoma (2 papers, 2020 to 2025). "Interestingly, MZB-cells expressing MZB-1 correlate with a higher number of infiltrating CD8+ T-lymphocytes in the tumor environment of pancreatic carcinoma and are associated with a better prognosis for this neoplasm." (PMID 40784052, 2025). "MZB1 is also a biomarker of favorable prognosis in pancreatic cancer resected after the neoadjuvant chemoradiotherapy." (PMID 33336008, 2020).
plasmacytoma (2 papers, 2021 to 2026). Plasmacytoma is a localized mass of neoplastic monoclonal plasma cells that represents approximately 5% of all plasma cell neoplasms. "Here, using CRISPR/Cas9-edited J558 plasmacytoma cells, a mouse line that secretes IgA, we demonstrate that MZB1 and the J chain act sequentially to ensure proper IgA assembly." (PMID 42079662, 2026). "MZB1 co-precipitated with the ER multichaperone complex glucose-regulated protein 94 (GRP94)-binding immunoglobulin protein (BiP) in the mouse plasmacytoma cell line Ag8.653 that does not express immunoglobulins, so MZB1 may assist IgM assembly as a molecular chaperone." (PMID 33668983, 2021).
acute leukemia (1 paper, 2025). A clonal (malignant) hematopoietic disorder with an acute onset, affecting the bone marrow and the peripheral blood. "Myeloperoxidase (MPO)/lysozyme (LYZ) and marginal zone B and B1 cell-specific protein (MZB1)/brain and acute leukemia, cytoplasmic (BAALC) were respectively activated in the granulocyte-macrophage progenitor (GMP) and multilymphoid progenitor (MLP) clusters." (PMID 40036065, 2025).
acute lymphoblastic leukemia (1 paper, 2024). Leukemia with an acute onset, characterized by the presence of lymphoblasts in the bone marrow and the peripheral blood. "We also found that ARG1 gene expression was restricted to the single erythroid cell cluster that we termed ARG1-positive Orthochromatic erythroblasts and that late Erythroid cells lose S100A9 and gain MZB1 gene expression in case of acute lymphoblastic leukemia." (PMID 39267736, 2024).
bronchiolitis obliterans syndrome (1 paper, 2024). A lung disorder that is mainly associated with chronic allograft dysfunction after lung transplantation and that is characterized by inflammation and fibrosis of bronchiolar walls that reduce the diameter of the bronchioles and result in progressive and irreversible airflow obstruction. "They found that the Mzb1-expressing plasma cell population in the lungs with bronchiolitis obliterans syndrome increased more than the others." (PMID 38667182, 2024).
chronic lung disease (1 paper, 2023). According to the definitions of the American and British Thoracic Societies, including pulmonary functional tests, X-rays, and CT scans for items such as fibrosis, bronchiectasis, bullae, emphysema, nodular or lymphomatous abnormalities. "showing increased levels of MZB1 proteins in the lung tissue of several chronic lung diseases, including IPF, hypersensitive pneumonitis, and connective tissue disease-associated ILD, which have distinct but overlapping pathogenesis." (PMID 38094295, 2023).
colorectal cancer (1 paper, 2025). A primary or metastatic malignant neoplasm that affects the colon or rectum. "Notably, our GSEA links phenotypic changes to MZB1’s regulation of DNA damage response and cell cycle pathways, which aligns with recent findings in colorectal cancer, where MZB1 deficiency promotes genomic instability." (PMID 40391075, 2025).
Crohn disease (1 paper, 2024). A gastrointestinal disorder characterized by chronic inflammation involving all layers of the intestinal wall, noncaseating granulomas affecting the intestinal wall and regional lymph nodes, and transmural fibrosis. "For instance, three markers JCHAIN/IgJ, IGLL5 and MZB1, which are strong markers for B-cells, are also markers of plasmacytoid cells in Crohn's Disease mesenteric adipose fat." (PMID 38978787, 2024).
cutaneous melanoma (1 paper, 2020). A primary melanoma arising from atypical melanocytes in the skin. "According to the analysis, the expression level of MZB1 was significantly associated with pathologic-N (P = 0.046) and tumor status (P = 0.002) in patients with cutaneous melanoma." (PMID 33336008, 2020).
epilepsy (1 paper, 2017). A brain disorder characterized by episodes of abnormally increased neuronal discharge resulting in transient episodes of sensory or motor neurological dysfunction, or psychic dysfunction. "All genes except for IL20RB, PPP2R2D and MZB1 were more expressed in the RNCC group as compared to the Idiopathic Epilepsy group." (PMID 28622332, 2017).
Granuloma (1 paper, 2025). A compact, organized collection of mature mononuclear phagocytes, which may be but is not necessarily accompanied by accessory features such as necrosis. "In type 1 reaction samples MZB-1-positive cells were distributed in the papillary dermis and, in some cases, they were scarce or even absent around granulomas contrary to what was observed in tuberculoid leprosy samples." (PMID 40784052, 2025).
ischemia (1 paper, 2024). A hypoperfusion of the BLOOD through an organ or tissue caused by a PATHOLOGIC CONSTRICTION or obstruction of its BLOOD VESSELS, or an absence of BLOOD CIRCULATION. "This suggests that Mzb1 is an important cardioprotective molecule and that loss of Mzb1 may be an important mechanism of ischemia-induced myocardial injury." (PMID 39206261, 2024).
ischemic heart disease (1 paper, 2024). "Our results suggest that puerarin may be an important adjunct medicine used for the treatment of ischemic heart disease or MI, and rescuing Mzb1 may be a new target for the prevention and treatment of cardiovascular diseases." (PMID 39206261, 2024).
leprosy (1 paper, 2025). Leprosy is a chronic infectious disease affecting primarily the skin and peripheral nervous system. "Type 2 reaction samples displayed MZB-1-positive cells forming small clusters, and like lepromatous leprosy samples, they showed a morphological appearance of plasma cells." (PMID 40784052, 2025). "CD20+ B-cells were abundant in tuberculoid lesions, whereas MZB-1 expression varied significantly among leprosy subtypes." (PMID 40784052, 2025). "Analyzing the expression of CD20 and MZB-1 in the studied groups, the authors found that in the Tuberculoid (TT) leprosy group, CD20 expression was higher than that of MZB-1." (PMID 40784052, 2025).
lymph node metastasis (1 paper, 2020). "Furthermore, the rate of lymph node metastasis is higher in the MZB1 high expression group than in the low expression group." (PMID 33336008, 2020).
metastatic melanoma (1 paper, 2020). A melanoma that has spread from its primary site to another anatomic site. "MZB1 (or pERp1) is upregulated in the metastatic melanoma and is a B cell-specific and endoplasmic reticulum (ER)-localized protein that is abundantly expressed in marginal zone B and B1 cells." (PMID 33336008, 2020). "Survival and multivariate Cox regression analyses revealed four vital genes, namely, POU2AF1, ITGAL, CXCR2P1, and MZB1, that affect the prognosis of patients with metastatic melanoma." (PMID 33336008, 2020).
nephritis (1 paper, 2015). Inflammation of renal tissue. "This more liberal view revealed FOS and LINC00339 (induction linked to nephritis), as well as MZB1 and TXNDC5 (induced in Type B patient samples), as increased in patients under steroid treatment." (PMID 26544975, 2015).
rectal cancer (1 paper, 2021). A primary or metastatic malignant neoplasm that affects the rectum. "In rectal cancer, COL1A1 and MZB1, as the key genes of rectal cancer, can interact with other genes correlated with shorter survival for patients." (PMID 33841514, 2021).
systemic sclerosis (1 paper, 2022). A chronic disorder, possibly autoimmune, marked by excessive production of collagen which results in hardening and thickening of body tissues. "Circulatory CK17, LRG1 and MZB1 concentrations were increased in Ssc patients." (PMID 36277429, 2022).
tuberculoid leprosy (1 paper, 2025). A principal or polar form of leprosy in which the skin lesions are few and are sharply demarcated. "In the present sample, MZB-1 expression was higher in tuberculoid leprosy than in the indeterminate form." (PMID 40784052, 2025).
ulcerative colitis (1 paper, 2025). An inflammatory bowel disease involving the mucosal surface of the large intestine and rectum. "In conclusion, we identified a close association between COL1A1, LOXL2, VWF, MZB1, and ERS in the pathogenesis of ulcerative colitis (UC)." (PMID 40607383, 2025).
tumor (24 papers, 2019 to 2026). "Specifically, MZB1 showed strong positive associations with anti-tumor immune populations, including CD8+ T cells (p < 0 .001) and dendritic cells (p < 0.001)." (PMID 40391075, 2025). "MZB1 was associated with higher accumulation of CD8+ tumor-infiltrating lymphocytes induced by chemotherapy." (PMID 34503206, 2021). "These pathways are associated with immunity and tumor proliferation, suggesting that MZB1 may regulate tumor progression by modulating immune responses and tumor proliferation." (PMID 40391075, 2025). "The results indicate that MZB1 within tumor cells plays a role in suppressing tumor proliferation and migration, functioning as a tumor suppressor gene." (PMID 40391075, 2025). "MZB1 showed significant positive correlations with B cells, T cells, and dendritic cells, which often exert anti-tumor effects." (PMID 40391075, 2025). "High MZB1 expression correlated with increased immune cell infiltration and higher immune scores, suggesting MZB1’s positive regulatory role in the tumor immune response, explaining the better prognosis for patients with high MZB1 expression." (PMID 40391075, 2025). "Our single-cell analysis revealed MZB1 expression in both tumor cells and immune subsets, while bulk RNA-seq correlations with immune infiltration scores suggest dual roles in cancer cell biology and immune modulation." (PMID 40391075, 2025). "MZB1 upregulated tumor-specific antibody secretion and decreased IL-10 expression by regulating the storage of calcium ions in the endoplasmic reticulum, which activated antitumor immunity." (PMID 36225934, 2022). "In borderline-resectable patients receiving neo-adjuvant chemotherapy, the expression of marginal zone B and B1-cell-specific protein (MZB1) was detected in the tumor stroma." (PMID 34503206, 2021). "The C2 cluster of cells were follicular B cells (MS4A1/CD20 and CD79A/B), which were found in lymphoid follicles of tertiary lymphatic structure within the tumor, and C0 and C4 clusters were antibody-secretory cells (MZB1 and SDC1/CD138)." (PMID 34367994, 2021). "The Chi-square analysis was performed to evaluate the connection between the expression of MZB1 and clinical characteristics such as gender, age, clinical stage, pathologic-T, pathologic-M, pathologic-N, and neoplasm status." (PMID 33336008, 2020). "The number of patients exhibiting a tumor-free status was higher in the MZB1 high expression group than in the low expression group." (PMID 33336008, 2020). "CTLA4, MZB1, NIP7, and BUB1B in ADC, as well as GNG11 and CCNB2 in SCC, are novel top hub genes in modules associated with tumour size, SUVmax, and recurrence-free survival." (PMID 31877723, 2019). "This review aims to synthesize current research findings on MZB1's functions across different immune cell types, elucidate its interactions with other immune regulatory factors, and explore its impact on the tumor microenvironment and immune-mediated disorders." (PMID 41635820, 2026). "Interestingly, the observed upregulation of MZB1 in various tumors presents an apparent paradox, given its documented tumor-suppressive properties." (PMID 40391075, 2025). "Importantly, those B lymphocytes of the TIGER database with the greatest increased expression of CD320 included MZB1+ and immunoglobulin producing B cell clusters, commonly found in the marginal zone of germinal centers and tumor TLSs." (PMID 39493449, 2024). "Notably, MZB1 (marginal zone B- and B1-cell-specific protein) was detected in the tumor stroma after neoadjuvant chemoradiotherapy and was positively correlated with elevated accumulation of CD8+ T lymphocytes." (PMID 36225934, 2022). "Moreover, MZB1 may exert an anti-tumor effect by activating the complement system, which aligns with its role in various tumors." (PMID 40391075, 2025). "Elevated MZB1 expression in plasma cells, T cells, and other immune cells in the TIME contributes to anti-tumor effects and inhibits tumor progression." (PMID 40391075, 2025).
tumor (continued). "BayeSpace‐enhanced spatial data revealed the abundant infiltration of T cells (CD3D, IL7R), B cells (MS4A1, MZB1), and cytotoxicity markers (GZMK) throughout tumor sections of HT samples, presenting an “immune‐activation” TME after HAIC therapy." (PMID 39686623, 2025). "Our data indicated that the “cold” tumor types like MB and EPN also contained the major classical immune cells, such as T cells (PTPRC, CD3D), B cells (CD79A, IGHG1, MZB1), and NK cells (KLRB1)." (PMID 38094301, 2023). "In particular, based on high level of SDC1, TNFRSF17, MZB1, CD38 and low level of CD19 and MS4A1, Cluster 0, Cluster 1 and Cluster 12 were defined as SDC1+ cells, namely plasma cell in HD controls and tumor cells in MM patient." (PMID 36532059, 2022). "In comparison with adjacent and precancerous tissues, we found a significant reduction of CD40+, CD27+, KLRB1+, and CCL5+ B cells (clusters 4, 9, 1, and 3, respectively) and MZB1+, DUSP1+, and CCL3+ plasma cells (clusters 5, 7, and 8) in tumor tissues." (PMID 34185431, 2021). "In analyzing B cells in the tumor microenvironment, B cells were separated into two clusters: one termed as follicular B cell, with high expressions of MS4A1, CD79B, CD52, and another termed as plasma cell, with high expressions of IGHG1, IGHG4 and MZB1." (PMID 38443340, 2024). "The MFP proteome was enriched for several immune-related and plasma proteins more indicative of inflammatory infiltration and chronic immune activation rather than tumor-specific remodeling including C1QB, CFH, MZB1, IGKV3-20, ORM2, ALB, and AZGP1." (PMID 41007761, 2025).
cancer (17 papers, 2020 to 2026). A tumor composed of atypical neoplastic, often pleomorphic cells that invade other tissues. "In summary, the tissue-specific expression pattern of MZB1 endows it with potential as both a diagnostic biomarker and therapeutic target, holding significant implications for the exploration of future cancer prognosis and treatment strategies." (PMID 41869442, 2026). "Further studies are needed to elucidate the molecular mechanisms underlying miR-1193’s regulation of MZB1 and its role in cancer pathways." (PMID 40391075, 2025). "Despite these controversies, MZB1 has been implicated in various human diseases including auto-immune disorders and cancer, which are possibly linked to abnormal levels of antibody production, transcytosis and secretion." (PMID 33668983, 2021). "Several studies concluded that some immune behaviors directed by MZB1 can prevent cancer progression, which is a promising therapeutic target." (PMID 36645174, 2023). "Further analysis showed that all of these dysregulated proteins had cancer-related associations, such as PDIA5, DEF6, MZB1, TXNDC5, YARS2, MGST1, and PIH1D1." (PMID 35958927, 2022). "Another future direction is to interpret the distinct function of the plasma-like specific, as well as the specifically expressed genes (such as CD38, MZB1), and their possible roles in cell-cell interactions and cancer-microenvironment co-evolution in NSCLC." (PMID 32580738, 2020). "The TIME dynamically regulates MZB1 activity, which in turn modulates cancer cell behavior." (PMID 40391075, 2025). "It is difficult to find a pattern for the altered expression of MZB1 in cancer." (PMID 33668983, 2021). "This phenomenon may be resolved by considering MZB1’s dual functionality in immune regulation – while it directly suppresses malignant cell migration through cancer cell-intrinsic mechanisms, it simultaneously engages in immunomodulatory processes within the TIME." (PMID 40391075, 2025). "The integrative analysis identified PROX1+ LEC subsets, JAM2+ BECs, COL1A1+ stromal cells, PTPRC+ leukocytes, including MZB1+ plasmablasts, KRT19+ cancer cells, and MKI67+-proliferating cells." (PMID 41249124, 2025). "Unbiased clustering using UMAP identified several cell types, including KRT19+ cancer cells, CD3E+ T cells, MS4A1+ B cells, MZB1+ plasmablasts, FLT3+ dendritic cells (DCs), and PROX1+ LECs, which were then visualized within the tissue context." (PMID 41249124, 2025). "It was noted that three of the four genes, i.e., MZB1, DERL3, and PSMD3, were more highly expressed in cancer tissues than in adjacent normal lung tissues." (PMID 34212001, 2021). "Anti-MZB1 treatment may not address the etiology or pathogenesis, yet it could be useful to measure the expression of MZB1 for prognosis and diagnosis of cancer." (PMID 33668983, 2021).
infection (2 papers, 2020 to 2026). The state of being infected such as from the introduction of a foreign agent such as serum, vaccine, antigenic substance or organism. "Integration with RNA-seq data revealed key genes (IL1R2, RBM34, EDEM3, and MZB1) potentially critical in early infection." (PMID 42087228, 2026).
connective tissue diseases (1 paper, 2023). "Overexpression of MZB1 has been observed in lung tissue from IPF and ILD associated with connective tissue diseases." (PMID 38094295, 2023).
renal disease (1 paper, 2023). "We also identified 3 proteins, (Staphylococcal nuclease domain-containing protein 1 (SND1), glycogen debranching enzyme (AGL) and marginal zone B- and B1-cell-specific protein (MZB1) that were associated with the presence of active renal disease." (PMID 37516862, 2023).
MZB1 also shares sentences with these, for which no sentence is quoted: COVID-19 (2 papers); leukemia (2); seminoma (2); 22q11.2 deletion syndrome (1); acute myocardial infarction (1); bladder cancer (1); cardiovascular diseases (1); cervical cancer (1); chronic lymphocytic leukemia (1); chronic periodontitis (1); diabetes (1); esophageal cancer (1); glioma (1); hypersensitive pneumonitis (1); influenza (1); lung adenocarcinoma (1); metastatic tumors (1); ovarian clear cell cancer (1); testicular cancer (1).